IL21 (interleukin 21)
Diseases named in the same sentence as IL21 in open-access papers (continued):
Sharing a sentence is not in itself a finding about the gene and the disease.
tumor (continued). "In this study, we demonstrated the effects of IL-15 and IL-21 cytokines on the functions of NK-exos, highlighting their significant role in inducing potent anti-tumor effects in HCC cells." (PMID 37484408, 2023). "The data suggest that in the TME of immunotherapy responders, FCRL4+ FCRL5+ B cells are driven by IFNα, TNF, and IL27 signals, and Tfhs are activated by these B cells to enhance anti-tumor immunity through secreting IL21." (PMID 36869384, 2023). "Human TH9 cells also promoted the cytotoxic function of CD8 T cells against autologous tumor cells in an IL-9- and IL-21-dependent manner." (PMID 37189417, 2023). "It has been affirmed that TFH cells recruited CD8 T cells and B cells by secreting CXCL13 and facilitated the maturation of B cells into antibody-producing plasmocytes by secreting interleukin 21 (IL-21), thereby affecting tumor microenvironment." (PMID 37371833, 2023). "In a mouse MC38 tumor model, we demonstrated that IL21 is produced by hyperactivated/exhausted CD4+ T cells in the TME." (PMID 37546701, 2023). "In this study, we aimed to investigate the synergistic anti-tumor effects of NK-exos stimulated with IL-15 and IL-21 (NK-exosIL−15/21) in Hep3B cells." (PMID 37484408, 2023). "IL-21 is a pleiotropic cytokine that promotes the activation, expansion, and survival of tumor-specific CD8+ cytotoxic T cells while also enhancing B-cell proliferation and antibody production." (PMID 37483629, 2023). "Shanghai Junshi Biopharmaceutical recently extended the half-life of IL-21 by fusing an anti-HAS single-domain antibody to improve the distribution of the drug in the tumor microenvironment." (PMID 36936961, 2023). "Recent studies have demonstrated the effectiveness of IL-21 in improving the anti-tumor effect of CAR-T cells." (PMID 38090585, 2023). "IL-21 tumor cell-targeting fusion protein was shown to induce the expansion of functional tumor-reactive CD8 T cells (PD-1intTim-3–CD8+) and promote the formation of memory T cells." (PMID 37189417, 2023). "Altogether, IL-21 can potently promote anti-tumor immune responses elicited by PD-1 blockade via several mechanisms." (PMID 37189417, 2023). "Here, we observed that, after treatment with an oncolytic VV armed with the cytokine IL-21, tumor macrophages tend to differentiate more markedly toward an M1 type." (PMID 35795092, 2022). "The proportion of CD4 and IL-21 positive cells in MPR tumor tissues were also significantly higher than that in treatment-naive and non-MPR tumor tissues." (PMID 35831283, 2022). "The increased levels of genes of Tfh cells in CD45+ TAS further supports B cell activation because Tfh cells secrete IL-21, a cytokine that enhances B cell differentiation into anti-tumor antibody secreting B plasma cells." (PMID 36230846, 2022). "The most essential cytokines in the anti-tumour response are IL-12, granulocyte-macrophage colony-stimulating factor GM-CSF, T cell growth factor IL-2, IL-2-related cytokines IL-15 and IL-21 and pro-inflammatory IFNγ and TNFα." (PMID 36140243, 2022). "Upon the recognition of tumor antigens, myeloid cells, especially dendritic cells (DCs) and macrophages produce inflammatory cytokines such as type-1 IFNs, IL-12, IL-15, IL-18, IL-21 involved in the natural killer (NK) cell tumor-killing response." (PMID 36341428, 2022). "These Bregs had a CD38+CD1d+IgM+CD147+ phenotype and were induced by IL-21 secreting regulatory T cells (IL-21 expression also being detected within the tumour tissue)." (PMID 35350071, 2022). "In our work, we found a greater increase in abundance of cluster-related and tumor-specific TCRs for cells cultured in IL-21+/anti-PD-1 conditions compared to IL-21+ alone." (PMID 35377314, 2022). "Of note, our study showed that enrichment of CD4+ T and B cells correlated with favorable clinical outcomes in NSCLC, and that IL-21 is critical for tumor control and B cells class switching to anti-tumor IgG1 and IgG3 isotypes." (PMID 35831283, 2022).
tumor (continued). "B cell IgG subclasses IgG1 and IgG3 played a critical role in anti-tumor immune response in tumor lesions, and this process was driven by increased IL-21 secreted by infiltrated T follicular helper (Tfh) cells after neoadjuvant chemoimmunotherapy." (PMID 35831283, 2022). "The IL-21 produced by Thf cells has been shown to be necessary for the inhibition of tumor and CD8 cell function." (PMID 36686480, 2022). "Production of IL-21, CXCL13, and infiltration by cytolytic CD4 and CD8 T cell infiltrates associate with IMAE development in tumor models and human plasma." (PMID 36314014, 2022). "Fusing engineered IL-21 with existing immunotherapies can elicit robust anti-tumor immune responses." (PMID 35831283, 2022). "Current evidence suggests that Tfh cells produce IL-21, crucial for B cell activation and tumor-infiltrating CD8+ T cell effector function, enhancing antitumor immunity and ICB response." (PMID 36588538, 2022). "The use of cytokines derived from the IL-2 family, such as interleukin IL-2, IL-7, IL-15, and IL-21, to stimulate the anti-tumor response is prevailing in the field of immunotherapy." (PMID 36275766, 2022). "Interleukin-21 (IL-21) is an extremely attractive cytokine in the context of anti-tumor immunotherapy as it can safely and effectively enhance immunity to tumors through multiple mechanisms." (PMID 35795092, 2022). "In murine tumor models, intratumoral injection of IL-21 strongly inhibited tumor growth and increased the frequency of tumor-infiltrating CD8+ T cells and mice survival." (PMID 35432319, 2022). "GPC3-CAR co-expressing IL-21 and IL-15 have demonstrated superior in vitro and in vivo expansion, persistence and anti-tumour activity." (PMID 35158772, 2022). "Plasma IL-21 level was also elevated after neoadjuvant chemoimmunotherapy in our single-cell study cohort, and higher IL-21 concentration was consistent with less residual viable tumor cells (RVT)." (PMID 35831283, 2022). "Combination of IL‐21 with anti‐PD‐1 or anti‐CTLA‐4 therapy in animal tumor models resulted in the augmented intra‐tumoral infiltration of CD8+ T cells, along with their increased proliferation and a higher proportion of effector memory T cells." (PMID 35301813, 2022). "In contrast, IL-5, IL-17A, IL-21, IL-22, and TGFβ concentrations in the tumour tissue of IL-9 knockout mice were significantly reduced compared with wild-type mice, indicating that IL-9 controls the production of Th2- and Th17-associated cytokines." (PMID 35793807, 2022). "Collectively, neoadjuvant pembrolizumab and chemotherapy increased Tfh cell infiltration and IL-21 secretion within the tumor tissues to promote anti-tumor response." (PMID 35831283, 2022). "IL-15, a type I cytokine together with IL-2, IL-4, IL-7, IL-9, and IL-21, promotes survival of T, B, and NK cells by binding to IL-15α, encoded by IL15RA, negatively regulating both carcinogenesis and tumor growth." (PMID 36432658, 2022). "Despite the gradual decrease in IL-21 in mice tumour tissues, overall extended survival was observed in these mice." (PMID 35805007, 2022). "To check if IL-21 is involved in neoadjuvant chemoimmunotherapy induced B cell class switching, we analyzed the characteristics of these IL21-producing cells in our scRNA data and found that they were most prevalent in tumor tissues." (PMID 35831283, 2022). "Here, we report that EVs derived from human NK-92 cells stimulated with IL-15 + IL-21 show enhanced cytotoxic capacity against tumor cells." (PMID 34316033, 2022). "In this tumor model, the enhanced anti-tumor effects of IL-1β-treated Th9 cells were indirect and required IL-21 priming of CD8 T cells and natural killer (NK) cells." (PMID 36389679, 2022). "In spleen cell supernatants, IFN-γ, IL-4, IL-1β, IL-6, IL-13, MCP-1, and IL-21 were significantly higher in the tumour-bearing SID animals compared to the healthy controls." (PMID 36010845, 2022).
tumor (continued). "B cell-recognized antigens drive tumor-specific B cell and T follicular helper cell responses; tumor specific T follicular helper cells produce IL-21, which is critical for tumor control and tumor-infiltrating CD8 T cell effector function." (PMID 36058945, 2022). "Quantitative analysis of IL-21 gene mRNA in the tumor tissue showed the highest activity in the G1 degree of histopathological differentiation and was higher in G1 compared to the control group." (PMID 34300224, 2021). "Our recently published work has shown that interleukin (IL)-21-producing CD4+ T cells help to generate effector CD8+ T cells within the tumor, which results in enhanced tumor control." (PMID 33809259, 2021). "Here, the authors show a potential strategy to improve the therapeutic effects of anti-PD-1 antibody by simultaneously targeting IL-21 to tumor-reactive T cells in vivo." (PMID 33574265, 2021). "IL-21 primarily promotes anti-tumour responses by stimulating proliferation, survival, differentiation, and cytotoxicity in CD8+ T cells and NK cells." (PMID 34885108, 2021). "Batf−/− mice exhibited significantly lower numbers of tumor-infiltrating CD8+ T cells per mm3 of tumor volume as compared to wild-type controls following IL-21-producing CD4+ T cell ACT." (PMID 33809259, 2021). "The results showed that FOXP3+ and IL-21+ cells collocated in the same area in the tumor stroma and that the increased density of the IL-21+ cells was positively correlated with that of the FOXP3+ cells." (PMID 34026621, 2021). "Recent studies, carried out on animal tumor models, show that different cytokines, including GM-CSF, IL-7, IL-12, IL-15, IL-18 and IL-21, are also able to limit tumor growth." (PMID 34208413, 2021). "IL-21 secretion by TH9 has also been shown to increase during anti-tumor response, which stimulates IFN-γ production by CD4+ T cells and is also involved in NK cell activation." (PMID 34012451, 2021). "Next, flow cytometric analysis showed that the frequency of tumor-infiltrating IL-21+CD4+ T cells positively correlated with that of FOXP3+CD25+CD4+ T cells, which supported our immunohistochemical results." (PMID 34026621, 2021). "A recent study evaluated the importance of intra-tumoral delivery of IL-21 using tumor cell lines expressing human EGFR (hEGFR) epitope and anti-hEGFR monoclonal antibody (Erbitux)-IL-21 fusion protein (Erb-IL-21)." (PMID 33777008, 2021). "Here, we examined the antitumor function of a half-life extended IL21 alone and in combination with PD-1 blockade using preclinical mouse tumor models." (PMID 34869384, 2021). "Results showed that the tumor-specific killing ability of HER-2 CAR-T cells was enhanced by addition of IL-21 at all E:T ratios." (PMID 34179083, 2021). "Use of cytokines like IL-2, IL-15, IL-12, IL-21 and IL-18 is considered a promising approach to induction of more efficient NK cell activation at tumor sites, while IL-15 and IL-21 can enhance NK cell cytotoxicity." (PMID 34177887, 2021). "IL-21 can be used therapeutically to enhance the killing function and tumor infiltration of CD8+ T cells." (PMID 34158852, 2021). "We subsequently evaluated the clinical relevance of the increased frequency of tumor-infiltrating IL-21-producing cells in 102 HNSCC patients using IHC." (PMID 34026621, 2021). "So far, no studies have been conducted to evaluate the expression of IL-21 in tumor tissue and the concentration in serum and peritoneal fluid." (PMID 34300224, 2021). "Collectively, these data demonstrate that combination therapy continually promotes the type 1 immune response over time and IL21 in particular greatly increases the tumor-antigen specific T cell in the periphery." (PMID 34869384, 2021). "We first examined the prevalence of tumor-infiltrating Tregs and IL-21+ cells using immunohistochemical staining for FOXP3 and IL-21." (PMID 34026621, 2021).
tumor (continued). "The present study aimed to evaluate the mechanisms by which IL-21-mediated inflammation regulates the generation and function of Tregs in the tumor microenvironment." (PMID 34026621, 2021). ".There data suggested the Tregs induced by tumor explant with the treatment of anti-PD-1 or/and anti-IL-21 are expectedly suppressive as the Tregs induced by tumor explant alone." (PMID 34026621, 2021). "In a variety of tumor types, IL-21 induced Granzyme B-Expressing Breg cells has been found to modulate cellular adaptive immune responses by promoting tumor avoidance mechanisms against anti-tumor immune attack." (PMID 35095898, 2021). "To expand the understanding of the correlations between IL-21, PD-L1, and Tregs in the tumor microenvironment and their prediction of disease prognosis, we detected the expression of IL-21, PD-L1, and FOXP3 in 102 newly diagnosed HNSCC patients." (PMID 34026621, 2021). "Prior to ACT, tumor-specific CD4+ T cells were cultured in Th17 skewing conditions to produce IL-21, as we have previously published." (PMID 33809259, 2021). "Treatment with recombinant CXCL13, IL-21 and Tfh cells alleviated tumor growth and enhanced the infiltration of CD8+ T cells and B cells, as well as B cell maturation in a PDAC mouse model." (PMID 34359579, 2021). "Our findings suggest that IL21 differentially acts on DC1s vs DC2s to promote the CD8+ T cell-mediated anti-tumor immune response." (PMID 34869384, 2021). "In this study, we established the critical role of the IL-21–BATF pathway in maintaining functional tumor-reactive CD8+ T cells in cancer." (PMID 33809259, 2021). "Here, we found that IL21 increases the number of tumor-antigen-specific T cells in the spleen in vivo." (PMID 34869384, 2021). "According to the authors, in vivo treatment with IL-21 leads to complete regression of FC-muMCL1 tumor in syngeneic mice through NK and T cell dependent mechanisms." (PMID 34300224, 2021). "In this study we first examined the therapeutic efficacy of a half-life-improved IL21 in preclinical mouse tumor models." (PMID 34869384, 2021). "Surface markers (PD1 and ICOS) had similar expression panels in tumors and spleens, and significantly different expression levels of functional effectors (CXCL13 and IL-21) reflected the diverse status of tumor-infiltrating Tfh cells exposed to tumor antigens." (PMID 34359579, 2021). "M2 macrophages, which are activated by the stimulation of IL-4, IL-13, or IL-21, are involved in wound repair, homeostasis, and tumor metastasis and tumor promotion." (PMID 33866463, 2021). "Tumor-bearing mice were treated with intraperitoneal (i.p.)injections of anti-PD-1 antibody, an equimolar mixture of PD-1Ab and IL-21, or PD-1Ab21 alone." (PMID 33574265, 2021). "Th9 cells, which are significantly increased in the peripheral blood of breast cancer patients, act via the secretion of both IL-9 and IL-21, which promotes cytotoxicity of tumor-specific CTLs." (PMID 34944921, 2021). "It is thus possible that IL-21 selectively support a local immunosuppressive environment, whereas systemic application of IL-21 activates cytotoxic T or NK cells with anti-tumor activity at tumor-distant sites." (PMID 34026621, 2021). "As such, CCL21 and IL-21 are potent activators of the immune system when used together for tumor therapy." (PMID 33802281, 2021). "It has been noted that IL-21 exerts diverse regulatory effects on healthy and tumour cells depending on the type of cell, stage of differentiation and type of stimulus." (PMID 34572910, 2021). "The levels of CXCL13 and IL-21 expressed by tumor-infiltrating Tfh cells in patients who received neoadjuvant chemotherapy was higher than those in patients who had not, although the proportion of Tfh cells showed no obvious difference." (PMID 34359579, 2021). "IL-21 is a pleiotropic cytokine that is produced by T cell subsets and enhances the survival and anti-tumor activity of CD8+ T cells." (PMID 34572932, 2021).
tumor (continued). "Numerous studies suggested the clinical significance of Th-17 responses in contributing to poor survival outcome in HCC patients by the pro-tumor functions of IL-17, IL-21 and IL-22, including tumor proliferation and angiogenesis." (PMID 33805946, 2021). "Compared to the nontreated control group, some antitumor effects were observed in the group treated with anti-PD-1 in CT26 tumor model, and the groups treated with anti-PD-1 or PD-1Ab combined with IL-21 in the MC38 tumor model." (PMID 33574265, 2021). "Here, we demonstrate that IL-21 can be targeted to tumor-reactive T cells by fusion of IL-21 to anti-PD-1 antibody." (PMID 33574265, 2021). "Here, we engineered an anti-PD-1 antibody-based immunocytokine, denoted as PD-1Ab21, by fusing IL-21 to anti-PD-1 diabody to illustrate that cytokines can be targeted to tumor-reactive T cells in vivo to promote cancer immunotherapy." (PMID 33574265, 2021). "While IL-21 was able to inhibit cancer cell-mediated FOXP3 induction in the context of tumor supernatants, which was contrary to our study." (PMID 34026621, 2021). "Subcutaneous administration of IL-21 augmented tumor regression and increased tumor infiltration by CD8 + T cells." (PMID 34300224, 2021). "Such immunotherapeutic potential of IL-21 to stimulate anti-tumour immune responses is being clinically investigated in different cancers." (PMID 34572910, 2021). "In parallel, Tfh cells secrete the cytokine interleukin 21 (IL-21), which promotes the differentiation and maturation of B cells into plasma cells that produce tumor antigen-specific antibodies and thus, enhance the long-term anti-tumor immune response." (PMID 34359579, 2021). "Consistent with the in vitro gene expression data for VEGFA and VEGFB showing induction after IL-21 treatment of Farage cells, in vivo we observed promotion of tumour angiogenesis." (PMID 32704112, 2020). "A larger signal area was observed in the group treated with IL-21 confirming better tumour growth in these mice." (PMID 32704112, 2020). "In summary, our data showed an association of IL21+ and IL26+ immune cell infiltration, increased ADC, and aggressive tumor disease, most likely due to the activation of the key cancer signaling pathways ERK1/2 and STAT3 and formation of tumor colonies." (PMID 31948053, 2020). "The aim of the current study is to investigate the role of IL21 and IL26 on tumor progression as well as their association with changes in the tumor microarchitecture of PDAC that can be detected in vivo by DW-MRI." (PMID 31948053, 2020). "In contrast, therapeutic administration of a PD-1 × IL-21 fusion protein, has a significant inhibitory effect on the tumor growth and improves overall survival." (PMID 32457754, 2020). "For comparison, IL21 as “relative cytokine” secreted by Th17-like cells was used in the present study because we had shown previously that it enhances tumor cell invasion." (PMID 31948053, 2020). "We evaluated the plasma concentrations of Th1 (IL-2, IFN-γ, and TNF-α), Th2 (IL-4, IL-5, IL-6, and IL-10), Th9 (IL-9), and Th17 (IL-17A, IL-17F, IL-21, and IL-22) cytokines in tumor-bearing mice by flow cytometry." (PMID 32802733, 2020). "It has been demonstrated that IL-6 and IL-21 in the WM tumor microenvironment, induce tumor cell proliferation and IgM secretion." (PMID 32763516, 2020). "These promising results with ICRs have led to further ICR investigations, such as the novel IL-4 vs. IL-21 ICR (4/21) that promotes Th17-like polarization in CAR T-cells in response to IL-4 in the TME that resulted in improved tumor-clearance in vivo." (PMID 33643299, 2020). "It is possible that the presence of IL-7 and IL-21 in the tumor microenvironment reduced CD5 by modulating transcriptional and/or posttranscriptional control mechanisms although that possibility is not specifically addressed by our data." (PMID 33584650, 2020).